RNU1-35P (RNA, U1 small nuclear 35, pseudogene)
Gene: Small nuclear RNA gene on chromosome 8 (135,742,343 to 135,742,495, reverse strand). Ensembl gene ENSG00000199652.
Homologues: Orthologues: chimpanzee U1 (100% identical), macaque U1 (93% identical), mouse Gm23303 (73% identical), rabbit U1 (73% identical), guinea pig U1 (71% identical), pig U1 (69% identical), dog U1 (67% identical), rat U1 (56% identical). Paralogues in human: RNVU1-32 (82% identical), RNU1-115P (81% identical), RNU1-89P (80% identical), RNU1-1 (80% identical), RNU1-138P (80% identical), RNU1-2 (80% identical), RNU1-27P (80% identical), RNU1-28P (80% identical), RNU1-3 (80% identical), RNU1-4 (80% identical), RNVU1-18 (80% identical), RNVU1-29 (80% identical), and 134 more.